APOE (apolipoprotein E)
Diseases named in the same sentence as APOE in open-access papers (continued):
Sharing a sentence is not in itself a finding about the gene and the disease.
Obesity (continued). "Both APOE knock in (APOE KI) and APOE knock out (APOE KO) mice have been useful in studying the effects of obesity and HFD." (PMID 30586872, 2018). "It was proven that APOE knockout mice exhibit less body fat stores and smaller adipocytes and are more resistant to diet-induced obesity." (PMID 28163789, 2017). "These latest findings constitute a major “paradigm shift” from the existing perception that peripherally expressed APOE promotes obesity via receptor-mediated postprandial lipid delivery to WAT." (PMID 29770778, 2017). "These novel findings constitute a major paradigm shift from the widely accepted perception that APOE promotes obesity via receptor-mediated postprandial lipid delivery to WAT." (PMID 29770778, 2017). "Hub genes of GAL, APOE, APOC2, and NPPB have been demonstrated to be associated with obesity as follows: (I) GAL: Galanin peptides, as the protein for GAL, is undoubtedly involved in the regulation of food intake and body weight." (PMID 29132311, 2017). "Overall, it has been identified that APOE expression serves as a key peripheral contributor to the development of obesity and related metabolic dysfunctions." (PMID 29132311, 2017). "In an effort to investigate the mechanisms of APOE promoted diet-induced obesity, in a recent study, we employed four different mouse models: Apoe-/-, Apoe3brain, Apoe3knock-in, and apoe-/- infected with an adenoassociated virus expressing APOE3 (AAV-E3)." (PMID 29770778, 2017). "Although ApoE-/-TSP1-/- mice developed similar level of obesity as ApoE-/- mice, ApoE-/-TSP1-/- mice had reduced systemic inflammation and improved glucose tolerance and insulin sensitivity." (PMID 25803585, 2015). "In this sense, the fact that APOE-effect acts not only upon BMI but WG also lends support to the existence of APOE-dependent lipid-independent mechanisms regulating adipose tissue mass and thus obesity." (PMID 25268647, 2014). "Several studies have supported linkage to obesity phenotypes at chromosome 19q13, where APOE gene is located." (PMID 25268647, 2014). "Some studies have reported that blood lipid response to diet or obesity varies depending on APOE genotypes." (PMID 22844488, 2012). "APOE genotypes, SFA intake, and obesity were found to be associated with blood lipid levels in Lithuanian adult population." (PMID 22844488, 2012). "Our 4-week rimonabant treatment of ApoE*3Leiden.CETP transgenic mice in early stage of obesity showed similar reduction of plasma TC and a reduction trend of plasma TG." (PMID 21611179, 2011). "The strength of the relation and the similarity of the results obtained for both tested indicators of obesity provide firm evidence that APOE plays an important role in obesity development in the Roma population." (PMID 21244662, 2011). "The effects of rimonabant on lipid metabolism and body weight reduction in the early stage obesity were shown to be moderate in ApoE*3Leiden.CETP mice on high-fat diet." (PMID 21611179, 2011). "In summary, we proposed that 4-week rimonabant treatment has a moderate effect on liver lipid metabolism in the early stage of obesity of ApoE*3Leiden.CETP mice under current experimental conditions." (PMID 21611179, 2011). "We show here that apoA-I strongly stimulates apoE secretion, suggesting that in pathological conditions, such as obesity, the combination of low HDL-c levels (carrying apoA-I) and oxidative stress contributes to a major reduction in adipocyte apoE secretion." (PMID 20642861, 2010). "In fact, APOE knockout mice have less body fat stores, smaller adipocytes and they are more resistant to diet-induced obesity." (PMID 20540717, 2010). "The current widely used murine AAA models include Ang II infusion in apolipoprotein E deficient (ApoE−/−) mice, elastase infusion, and calcium chloride exposure, which are not physiologically relevant to obesity-related AAA in humans." (PMID 39872985, 2025).
Obesity (continued). "Similarly, we recently reported that APOE plays a tissue-specific role in diet-induced obesity: Brain-expressed APOE promotes obesity, while hepatically expressed APOE appears protective." (PMID 41354325, 2025). "Additionally, there were no significant vascular (blood pressure, cholesterol, fasting glucose, obesity) or genetic (ApoE) differences between clusters." (PMID 40463724, 2025). "In the future, it would be of interest to investigate how other influencing factors such as obesity, cholesterol levels, physical activity, smoking or genetics, e.g. APOE status, could impact automatic WML estimations." (PMID 39115640, 2025). "Lower biomarker status of vitamin B12, vitamin B6, and riboflavin were each independently associated with a 30–73% increased risk of cognitive dysfunction, after adjustment for age, sex, obesity, education, socioeconomic deprivation, and ApoE ε4 status in this study." (PMID 40717068, 2025). "The impacts of APOE genotype on responses to obesity have been mixed in prior studies." (PMID 39347015, 2024). "The ability of dietary supplementation or obesity to induce CVDs in rodent models without genetic modifications, such as low-density lipoprotein receptor and apolipoprotein E deficiency, has been the subject of significant debate in the scientific literature." (PMID 39770917, 2024). "In this study, we examined the association of the polymorphism rs4420638 A > G, tagging the LD block harboring the APOE and APOC1 genes, with the risk of obesity using BMI case-control groups of Portuguese children (normal-weight vs. overweight, including obesity)." (PMID 37328602, 2024). "Importantly, our study design allowed the testing of the effects of 17βE2 after the establishment of obesity across APOE genotypes." (PMID 39347015, 2024). "The SNP rs429358 (missense variant in APOE) is robustly associated with loss in BMI and weight, independent of baseline obesity, across men and women, across three global cohorts of European ancestry." (PMID 38987242, 2024). "ApoE+ MoMacs are also found in white adipose tissues during obesity, a condition conferring a training-like feature to MPs or during influenza-induced lung inflammation supporting the crucial role of ApoE for the development of functionally adapted macrophages during inflammation." (PMID 38671323, 2024). "Inflammatory pathways are implicated in pathological and normal age-related cognitive decline and represent one mechanism by which obesity and APOE may interact to affect vulnerability to AD and other age-related metabolic disorders." (PMID 36837905, 2023). "In addition, ApoE mRNA expression is decreased in F4/80+CD11c+ ATMs, which have been reported to be sensitive to macrophage activation in obesity, which dynamically influences the tissue microenvironment." (PMID 38062308, 2023). "Obesity induces the development of AD mainly through the regulation of lipid metabolism by APOE." (PMID 37686334, 2023). "Bioinformatics analysis revealed Apolipoprotein E (APOE) as the key target of obesity-induced AD." (PMID 37686334, 2023). "Although the APOE-ε4 allele confers a strong genetic risk for AD, it is unclear if late-life obesity poses a greater risk for APOE-ε4 carriers compared to non-carriers." (PMID 37731955, 2023). "Here, we defined a crucial role for ApoE in protecting HFD-induced obesity, hyperglycemia, and IR but at an inflammatory cost in WAT, which provides new insights into the diagnostic and therapeutic approach for obesity." (PMID 38062308, 2023). "A range of obesity biomarkers were significantly elevated in the obese samples: cholesterol, triglycerides, natural phospholipids, and lipid binding apolipoproteins, including lipid binding ApoE." (PMID 37414857, 2023).
Obesity (continued). "Next, further to evaluate the clinical relevance of ApoE expression with obesity, OAT samples were collected from 30 overweight/obese (BMI ≥ 24) subjects and 17 lean (BMI < 24) undergoing RNA-Sequencing (RNA-Seq) analysis (Cutoff: P-value < 0.05 and |Log2 (fold change) | > 0.3)." (PMID 38062308, 2023). "The differential effect of AD genetic risk on CA1 volume suggests late-life obesity is neuroprotective for APOE-ε4 non-carriers while particularly detrimental to brain health for APOE-ε4 carriers." (PMID 37731955, 2023). "Obesity is an important factor that links APOE, AD, CVD, and T2D." (PMID 36837905, 2023). "ApoE is a multifunctional lipoprotein with central roles in lipid metabolism, and our studies found that ApoE may be a key regulator in diet-induced obesity and lipid homeostasis." (PMID 38062308, 2023). "Our study also observed that obesity effects on hippocampal subfield volume may differ by APOE-ε4 carrier status." (PMID 37731955, 2023). "In conclusion, there is a correlation between obesity and AD, which is mainly due to the polymorphism of the APOE gene rather than adipose tissue distribution." (PMID 37686334, 2023). "Recent research, however, suggests environmental or health factors, such as obesity, may modify the influence of APOE-ε4 in some racial and ethnic groups." (PMID 37731955, 2023). "Diet‐induced obesity (i.e., western diet) in 5xfAD/human APOE‐ε4+/+ mice exhibit a significant increase in amyloid deposits, Aβ burden, and reactive gliosis compared to 5xfAD/human APOE‐E3+/+; suggesting that there is an interaction between obesity and APOE in increasing AD pathogenesis." (PMID 35128745, 2022). "We propose that interaction effects between APOE ε4 and obesity on the hippocampal formation may increase that region's vulnerability to subsequent neurodegeneration." (PMID 35303671, 2022). "•APOE modifies the effects of obesity on hippocampal size/complexity." (PMID 35303671, 2022). "Together, these findings suggest that APOE ε4 and obesity lead to metabolic alterations, including inflammatory processes, and may adversely interact with each other and with other genetic factors on brain structure and function." (PMID 35303671, 2022). "The majority of the main evidence includes oxidative-stress, inflammation, obesity, dysregulation of Apolipoprotein E (APOE), insulin degradation enzyme (IDE), Glucose Transporter type 4 (GLUT4), and Acetylcholinesterase (AChE), are linked to insulin resistance." (PMID 36092798, 2022). "Our reviewed studies considered the air pollution, stress, social interactions, blood pressure, physical activity, and obesity as potential mediators and sex, indicators of socioeconomic position learning opportunity index, and APOE ε4 as potential effect modifiers." (PMID 36141977, 2022). "Obesity develops much more rapidly, which could explain why we did not observe an effect of transient anti-obesity vaccination with pB1 on atherogenesis in ApoE knockout mice." (PMID 33916621, 2021). "Interactions between obesity and apoE genotype have been reviewed elsewhere and suggest differences in weight gain as a consequence of storage of lipids in adipose tissue could be a contributor to insulin resistance and glucose intolerance." (PMID 34545146, 2021). "Here, we investigate how diet induced obesity affects inflammation in the CNS in APOE mice." (PMID 34537055, 2021). "A controlled diet by feeding both apoE-/- and WT mice on the same high-fat diet, would result in a comparison between AS and obesity group instead, as WT mice on high-fat diet have been widely used as obesity model previously." (PMID 34277461, 2021). "Because of the reduced lumen stenosis in BT of GDF-15−/−/ApoE−/− mice after CED, we investigated whether GDF-15 deficiency affects obesity and blood lipid concentration." (PMID 34571994, 2021).
Obesity (continued). "ApoE's influence on the clinical aspects of COVID-19 may also be correlated with its intrinsic role in the pathophysiology of obesity." (PMID 34179542, 2021). "So far, there is no study on the relationship between obesity and apoE gene polymorphism in Chinese elderly schizophrenic patients, therefore, we conducted this cross-sectional study to investigate the relationship between APOE E4 and lipid metabolism and obesity." (PMID 34285334, 2021). "Several studies suggest a strong link between ApoE and overweight/obesity." (PMID 33626069, 2021). "At the same time, we also discussed the inner link between APOE E4 and obesity." (PMID 34285334, 2021). "In conclusion, developmental exposure to CPF, together with individual differences involving sex and the APOE genotype, may contribute to the global incidence of overweight and obesity." (PMID 33383760, 2020). "ApoE knockout (ApoE-/-) animal models provide valuable means for studying and exploring potential targets to suppress the burden of disturbed lipid metabolism-related diseases, such as obesity, cardiovascular diseases, and AD." (PMID 32344633, 2020). "ApoE*3Leiden.CETP mice rapidly developed obesity and were highly prone to cartilage degradation." (PMID 32456298, 2020). "While APOE genotype and obesity independently affect metabolism and cognition, they may also have synergistic effects." (PMID 31554665, 2019). "We have shown that resistin, a pro-inflammatory hormone secreted by murine adipocytes, was increased in the adipose tissue of our MHO model following 12 weeks of HFD feeding compared with atherosclerotic ApoE-/- mice and classical obesity diet-induced obesity WT mice." (PMID 30369883, 2018). "In addition, we found the fat mass and obesity-associated protein FTO, an AD risk factor which genetically interacts with APOE, was the most highly connected hub protein of the M1 module." (PMID 29490708, 2018). "In this study, we investigated, for the first time, the effects of PYC on the expression of genes related to the browning of WAT in ApoE-deficient mice fed with an HCD, which may provide a novel strategy for preventing and treating obesity." (PMID 29577045, 2018). "Besides its association with the lipid profile, some studies have demonstrated that the APOE gene influences characteristics of obesity." (PMID 30507998, 2018). "Although the impact of sex differences in the interactions among obesity, APOE, and AD risk has not been thoroughly addressed, AD is characterized by numerous sex differences." (PMID 28612048, 2017). "APOE gene is found to play a key role in modulating lipid metabolism and obesity." (PMID 28915562, 2017). "The important role of APOE in the clearance of TRLs from peripheral circulation led to a widely accepted perception among broader scientific community that APOE promotes obesity via receptor mediated postprandial lipid delivery to peripheral tissues, including BAT and WAT." (PMID 29770778, 2017). "How obesity and APOE interact to regulate AD pathogenesis remains to be determined." (PMID 28612048, 2017). "The goal of this study is to examine whether APOE genotype and obesity interact to promote AD pathogenesis." (PMID 28612048, 2017). "Another study evaluated the effects of quercetin on obesity in overweight-obese subjects with various apolipoprotein E (APOE) genotypes; the authors reported that quercetin (150 mg/day/subject) decreased the waist circumference and triacylglycerol concentration." (PMID 29138673, 2017). "Many studies simply control for APOE genotype rather than considering its potential moderating role in the relationship between obesity and AD risk." (PMID 28612048, 2017). "There are several other mechanisms besides metabolic impairment that may contribute to the observed interactions among obesity, APOE, and AD-like pathology." (PMID 28612048, 2017).
Obesity (continued). "Our findings suggest that APOE genotype affects the relationship between obesity and AD, such that APOE4 carriers may be more susceptible to obesity-associated risks than APOE3 carriers." (PMID 28612048, 2017). "The present study investigated the MMP-12 function in obesity-induced glomerular fibrogenesis and inflammation in mice lacking apolipoprotein E alone (apo E−/−)—which are predisposed to obesity—or both apo E and MMP-12 (apo E−/−MMP-12−/−) that were maintained on HFD for 3, 6, or 9 months." (PMID 26822129, 2016). "Additionally, the ApoE, PTP1B and RBP4 lipometabolic regulators linked with obesity and insulin resistance were upregulated in PLB4 mouse liver, suggesting decreased hepatic insulin sensitivity." (PMID 27138913, 2016). "The association of APOE genotype with hypoalphalipoproteinemia was independent of obesity-related traits." (PMID 27724906, 2016). "In conclusion, our data reported that the APOE genotype and haplotype were significantly associated with plasma TC and LDL-C level in Vietnamese children; the association of APOE genotype with hypoalphalipoproteinemia was independent of obesity-related traits." (PMID 27724906, 2016). "We showed that TSP1 deficiency did not affect the development of diet induced obesity in ApoE-/- mice." (PMID 25803585, 2015). "Altogether, lack of adipocyte-derived apoE does not influence obesity and associated metabolic disturbances in our conditional deficiency model." (PMID 26695075, 2015). "We show that lipid modulating genes are dynamically regulated during adipogenesis and that variants near SORT1 and APOE influence lipid levels independent of obesity in children." (PMID 26375028, 2015). "Genetic studies have provided an opportunity to determine which proteins link vitamin D to obesity pathology, including the vitamin D receptor, toll-like receptors, the renin-angiotensin system, apolipoprotein E, vascular endothelial growth factor, and poly (ADP-ribose) polymerase-1." (PMID 23800102, 2013). "Previous work has demonstrated that hypercholesterolaemic homozygous apolipoprotein-E-deficient mice fed a high-fat diet are resistant to ischaemic AKI in the absence of obesity." (PMID 24172587, 2013). "To date, this is the first study that assessed the frequencies of the APOE allele, the association of the APOE genotypes with lipid levels, and the effect of the interaction between APOE genotypes, SFA intake, and obesity on lipid levels in the adult Lithuanian population." (PMID 22844488, 2012). "Based on our study, we proposed that the rimonabant intervention on early obesity of ApoE*3Leiden.CETP mice would affect plasma and hepatic lipid metabolism relative to the non-treated controls, leading to increased HDL-C concentrations and decreased VLDL/LDL-C levels." (PMID 21611179, 2011). "Thus, in the present study, we examined APOE rs769450, rs405509 and rs439401 in relation to obesity and related metabolic quantitative traits in a group of middle-aged Danish men according to their perceived stress levels." (PMID 21283811, 2011). "On the other hand, APOE E4 shows some advantages at earlier life stages in comparison to E3 such as improved neural and cognitive development in youth and decreased infant and perinatal mortality, and was recently found to have a protective effect against obesity and T2D." (PMID 40323280, 2025). "Interestingly, females often show greater APOE-related CNS effects of obesity than males." (PMID 39347015, 2024). "Thus, our studies might provide new sights into ApoE, which is required for obesity-induced hyperglycemia, hyperinsulinism, and adaptive inflammation responses but diminishes the tolerance towards a subsequent metabolic inflammatory challenge." (PMID 38062308, 2023). "Furthermore, we innovatively revealed the complexity of the association between obesity and AD via Mendelian randomization, which was mainly determined by APOE polymorphism rather than body fat distribution." (PMID 37686334, 2023).